TRPC3 (transient receptor potential cation channel subfamily C member 3)
Diseases named in the same sentence as TRPC3 in open-access papers (continued):
Sharing a sentence is not in itself a finding about the gene and the disease.
cancer (30 papers, 2009 to 2025). A tumor composed of atypical neoplastic, often pleomorphic cells that invade other tissues. "TRPC3 has also been implicated in a number of cancers as a driver of tumour cell proliferation but targeting TRPC3 as a therapeutic strategy for cancer has not yet been explored." (PMID 37759438, 2023). "This suggests that stromal cells senescence caused by TRPC3 downregulation facilitates cancer progression mainly via the production of a pro-inflammatory and pro-tumour SASP." (PMID 35177596, 2022). "For example, TRPA1, TRPC1, TRPV4, TRPV5, and TRPV6 exhibited higher CNV amplification, while TRPV1, TRPV2, TRPV3, and TRPC3 exhibited frequent CNV loss in cancer." (PMID 35614079, 2022). "Thus, our results reveal that TRPC3 suppression in both normal and cancer-associated fibroblasts modify the behaviour of epithelial cancer cells." (PMID 35177596, 2022). "Additionally, investigating whether an association of episodes of pain symptoms of the cancer patients and their relative TRPC3/TRPC7 activation in the tumor tissue exists is desirable." (PMID 35330477, 2022). "This positions TRPC3 as a potential therapeutic target to disrupt pathological exosome-mediated signaling in cancer." (PMID 40813985, 2025). "This lncRNA works as a “sponge” for miR-26a-5p to promote the expression of TRPC3 (Transient Receptor Potential Cation Channel Subfamily C Member 3) ultimately driving proliferation and invasion by the cancer cells." (PMID 40076754, 2025). "In our study, we aimed to elucidate the migration abilities of cancer cells by using wound healing assays and immunostaining of focal adhesions to assess the effect of TRPC3 knockdown on cell migration in both collective and single-cell contexts." (PMID 39436410, 2025). "In senescent cancer-related fibroblasts, the stromal cell with downregulation of TRPC3 would increasingly product ROS and secreted SASP which facilitating the growth of cancer cells." (PMID 38851002, 2024). "We also analysed the effect of L687 on ASO activity in TRPC3/C6/C7-expressing cancer cells and in a mouse xenograft model of cancer with transplanted cells." (PMID 38621757, 2024). "TRPC3 is upregulated in numerous cancers and has been proposed to promote tumorigenesis by mediating sustained elevated Ca2+ signalling." (PMID 38938673, 2023). "TRPC3 mRNA is elevated in cancer tissue compared to control tissue and augmented in tumors with lymph node invasion compared to tumors without signs of lymph node invasion." (PMID 35330477, 2022). "Cellular senescence evoked by TRPC3 downregulation in stromal cells displays a proinflammatory and tumour-promoting secretome that encourages cancer epithelial cell proliferation and tumour growth in vivo." (PMID 35177596, 2022). "In vivo, TRPC3 expressed on MSCs also contributed to the tumorigenesis and progression of cancer cells." (PMID 35870973, 2022). "In particular, three out of the selected ‘prostate-associated’ channels are overexpressed in PCa ECs and have marked effects on the main EC properties including proliferation (TRPV2), TEC-mediated crosstalk with cancer cells (TRPC3) and angiogenesis (TRPA1)." (PMID 31288452, 2019). "After 2 days, 6 DEG were related to cancer such as Adcyap1, Ramp1, and Trpc3 which were down-regulated." (PMID 29950665, 2018). "The sizes of PCR products for TRPC3 and C6 found in the cancer tissues appeared to be consistent to that found in the MDA-MB-231 cell line." (PMID 19689790, 2009). "TRPC3 is present in normal tissues but it is significantly up regulated in the cancer tissues by an average of over five fold (F = 5.4 p = 2.5 n = 5)." (PMID 19689790, 2009). "TRPC3 and TRPC6 have been implicated in DOX-mediated cardiotoxicity, whereas TRPC5 has been associated with P-glycoprotein-induced chemoresistance in cancer cells." (PMID 39594815, 2024). "Moreover, a role of TRPC3 in immunity, cancer, and tissue remodeling has been proposed, generating much interest in TRPC3 as a target for pharmacological intervention." (PMID 30037143, 2018).
cancer (continued). "In particular, TRPC3 was found as an ion channel that governs proliferation and migration of a variety of tumor cells, including melanoma, lung, bladder, ovarian, and breast cancers." (PMID 30037143, 2018). "Our findings suggest a mechanism whereby AA, through direct inhibition of Ca2+ entry via TRPC3 channels may play a role in cancer cell proliferation and invasion." (PMID 22692672, 2012). "Given that EVs released by cancer cells with disrupted Ca2+ signalling can exhibit enhanced metastatic capacity, we hypothesized that EVs induced by TRPC3 activation may contribute to OC tumorigenesis through enhancing cell proliferation." (PMID 38938673, 2023). "Recent studies have elucidated the crucial role of TRP channels, specifically TRPC3,TRPC5,TRPV4 TRPML3, in regulating the release, cargo content, and downstream effects of cancer-derived exosomes within the tumor microenvironment (TME)." (PMID 40813985, 2025). "GSEA enrichment revealed the core genes of the signature, TRPC3 and TRPC7, were involved in several cancer-related pathways." (PMID 35330477, 2022). "Our study revealed that TRPC3 is oncogenic in MDA-MB-231 cells through the increased production of IL-8, an important molecule in cancer development." (PMID 35216080, 2022). "Although TRPC3 and TRPC7 mediate store-operated Ca2+ entry (SOCE) potentiating acceleration of cancer cell growth, seldom does the study point out the function of TRPC7 in cancer development." (PMID 36045706, 2021). "In addition to cancer, the TRP channels, namely the TRPC3 group, regulate functions in neurons and are involved in various neurological and psychiatric disorders." (PMID 36880517, 2023). "We further found a significant negative correlation of the expression between PLAA and TRPC3 mRNA in 56 cancer samples, and IHC staining assay also showed the negative correlation between PLAA and TRPC3." (PMID 35869392, 2022). "As both other TRPC subgroup members TRPC3 and TRPC6, TRPC7 is suggested to play a potential role in the physiology and pathology of neurological disorders, in the cardiovascular system, and in cancer cell growth and progression." (PMID 34828338, 2021).
tumor (16 papers, 2018 to 2024). "Our results demonstrate that senescence is associated with mitochondrial dysfunction depending on TRPC3 bioavailability and is characterised by the release of pro-inflammatory chemokines, cytokines and other tumour-promoting molecules." (PMID 35177596, 2022). "The waterfall chart of mutation analysis shows that in tumor samples positive for TRPC3 expression, they are also often highly mutated in KRAS gene loci (89.7%), and that the specific mutation type is missense mutation." (PMID 35330477, 2022). "In this study, immunostains were performed with an anti-TRPC3 antibody (cat: 54616, AnaSpec, San Jose, CA, USA); the tumor cells showed strong cytoplasmic staining, whereas control pneumocytes were either negative or weakly positive." (PMID 37240443, 2023). "After TRPC3 knockdown, the ability of MT- CAFs to promote tumor migration and invasion was impaired." (PMID 35870973, 2022). "Our results suggest that TRPC3 expression is associated with a poor prognosis, and that the role of TRPC3-positive mesenchymal cells is more important than that of TRPC3-positive tumor cells." (PMID 35870973, 2022). "The results showed that a-SMA and TRPC3 were co-expressed, which suggested that TRPC3 was expressed on the surface of the mesenchymal cells in the mouse tumor tissues." (PMID 35870973, 2022). "TRPA1, TRPV2, and TRPC3 were shown to be up-regulated in three different endothelial cell lines established from PCa patients as well as in endothelial cells lining tumor capillaries in vivo." (PMID 36430727, 2022). "The in vivo results also suggest that TRPC3 is closely related to the ability of CAFs to promote tumor progression." (PMID 35870973, 2022). "TRPC7 expression trend is opposite to TRPC3 revealing higher expression value is higher in adjacent samples than in tumor tissues (p = 4.3 × 10−3)." (PMID 35330477, 2022). "Knockdown of TRPC3 in MSCs obviously decreased tumor growth and progression compared to co-culture with HCT116 and MSC cells." (PMID 35870973, 2022). "The correlation between the expression of TRPC3 in tumor cells or tumor stromal cells and patient prognosis was further analyzed." (PMID 35870973, 2022). "This was consistent with the finding that TRPC3 expressed on MT-CAFs has a positive effect on tumor-cell proliferation and metastasis in vitro." (PMID 35870973, 2022). "As a regulator, TRPC3 was reported to promote the migration and invasion of several different tumor cell types." (PMID 35870973, 2022). "To further verify the pathological role of TRPC3 in vivo, we constructed a xenograft tumor model by subcutaneously injecting cells into nude mice." (PMID 35870973, 2022). "Inhibition of TRPC3 expression weakened the ability of CAFs to promote tumor cell proliferation, invasion and migration, while a TRPC3 agonist alone was able to promote tumor cell proliferation, invasion and migration." (PMID 35870973, 2022). "The importance of TRPC3 as a regulator of migration and invasion has been studied in several different tumor cells." (PMID 32138386, 2020). "We firstly used an independent dataset, GSE28735, to verify the expression validation of the genes, and the results suggest that TRPC3 is significantly upregulated in tumor tissues compared to adjacent tissues, with statistically significant differences between groups (p = 8.8 × 10−3)." (PMID 35330477, 2022). "To determine whether TRPC3 in mesenchymal cells or tumor cells was more essential to clinical outcomes, we compared the ratio of tumors with TRPC3 positive mesenchymal cells in the TC and DN groups." (PMID 35870973, 2022). "To assess further our hypothesis that TRPC3 suppression in stromal cells favours a senescent pro-tumour microenvironment, we have conducted in vivo experiments." (PMID 35177596, 2022). "TRPC3 expression in MT-CAFs also affects their ability to promote tumor progression." (PMID 35870973, 2022).
tumor (continued). "This conclusion is also applicable for samples with positive TRPC7 mRNA abundancy (89.0%), meaning that in any case of positive signal for TRPC3 or TRPC7 expression in a given tumor, the tumor cells frequently possesses the prominent mTOR pathway activating mutation." (PMID 35330477, 2022). "We next analyzed whether MT-CAFs with TRPC3 knockdown affected tumor metastasis by co-culturing HCT116 cells with MT-CAFs with or without TRPC3 knockdown." (PMID 35870973, 2022). "TRPC3 also enhanced melanoma cell migration and tumor formation both in vitro and in vivo." (PMID 32138386, 2020). "Immunohistochemistry did not confirm TRPC3 expression patterns in PTEC mRNA profiling, revealing negative TRPC3 staining in ECs in all normal areas (n = 10/10 patients) (Figure 2aci), but only one tumor area (n = 1/10) showed faint positive TRPC3 staining in ECs (Figure 2acii)." (PMID 31288452, 2019). "Therefore, the administration of L687 or other TRPC3/C6 activators could facilitate ASO delivery specifically into targeted tumour cells." (PMID 38621757, 2024). "Furthermore, we adopted a xenograft tumor model to verify the function of TRPC3 in CAFs in vivo." (PMID 35870973, 2022). "On the other hand, we show that elevated expression of TRPC3 is associated with shortened RFS, OS, and DSS, is upregulated in N1 compared to N0 tumor cases, and tends to be enriched in the invasive tumor area; our data indicates TRCP3 may possess pro-tumorigenic potential in PAAD." (PMID 35330477, 2022). "And syncytin-1 can also affect various signal pathways to induce tumorigenesis, such as TRPC3, DISC1, SK3, Akt and Erk1/2, promoting the proliferation and invasion of tumor cells and improving the ability of distant metastasis." (PMID 37326913, 2023). "Here the authors show that TRPC3 limits senescence by inhibiting IP3R-mediated Ca2+ release and ER mitochondria Ca2+ transfer and that the downregulation of TRPC3 in stromal cells affects SASP production and tumour progression." (PMID 35177596, 2022). "Altogether, our findings pinpoint TRPC3 as a key regulator of intracellular Ca2+ events engaged in senescence affecting SASP production and thereby tumour progression." (PMID 35177596, 2022). "Finally, we discuss the role of endothelial TRP channels in aberrant tumor vascularization by focusing on TRPC1, TRPC3, TRPV2, TRPV4, TRPM8, and TRPA1." (PMID 32038296, 2019). "However, the effect of TRPC3 expressed on MT-CAFs in the tumor microenvironment has not been reported." (PMID 35870973, 2022). "In addition, the DFS was significantly shorter in TRPC3-positive patients (including tumor-positive and stromal cells) than in TRPC3-negative patients." (PMID 35870973, 2022).
kidney disease (5 papers, 2015 to 2025). "TRPC3 is a promising therapeutic target for aging-associated renal disorders." (PMID 38415902, 2024). "As with other kidney disease models that we examined, protein overload in wild-type rats was associated with a marked increase in the net abundance of TRPC6 and TRPC3 in renal cortex." (PMID 35805070, 2022). "Although TRPC5 and TRPC6 have received the most attention, accumulating evidence suggests that TRPC3 also plays a role in kidney diseases." (PMID 31877991, 2019). "Trpc3 KO significantly improved the renal disorder and cell senescence in D-gal-induced mice." (PMID 38415902, 2024). "This review highlights the data implicating TRPC6 and other TRPC family members in both genetic and non-genetic forms of kidney disease, focusing on TRPC3, TRPC5, and TRPC6 in a cell type (glomerular podocytes) that plays a key role in proteinuric kidney diseases." (PMID 31877991, 2019).
cardiovascular diseases (4 papers, 2019 to 2024). "These structural insights into the function of TRPC3 are invaluable for understanding the role of the TRPC subfamily in health and disease, in particular for cardiovascular diseases, in which TRPC3 channels play a major role." (PMID 38890374, 2024).
neurological disorders (4 papers, 2020 to 2025). "Our results indicate that TRPC3 contributes to hemodynamic responses associated with cortical spreading depression and could be a novel therapeutic target for a host of neurological disorders." (PMID 37628789, 2023).
adenocarcinoma (2 papers, 2013 to 2023). A common cancer characterized by the presence of malignant glandular cells. "For example, we know that pulmonary adenocarcinoma is strongly positive for TRPC3, but we do not know whether or not other adenocarcinomas are also TRPC3-positive." (PMID 37240443, 2023).
cardiac disease (2 papers, 2007 to 2022). "Nonetheless, our finding that TrpC3 is a common element in the activation of gene expression in response to multiple stimuli suggests that it might be a useful target for the development of pharmacological blockers to treat heart disease." (PMID 17726532, 2007).
metabolic disorders (1 paper, 2022). "We found that TRPC3 is a key factor in irisin-induced beiging of MSCs, which may provide a new target pathway in addressing metabolic disorders." (PMID 35501783, 2022).
TRPC3 also shares sentences with these, for which no sentence is quoted: cerebellar ataxia (11 papers); cardiac arrhythmias (3); essential hypertension (3); asthma (2); bladder cancer (2); cardiomyopathy (2); dilated cardiomyopathy (2); hypertrophy (2); metabolic syndrome (2); myocardial ischemia (2); neurodevelopmental disorder (2); Type 2 Diabetes (2); acute respiratory distress syndrome (1); airway hyperresponsiveness (1); allergic asthma (1); Allergy (1); amyotrophic lateral sclerosis (1); autosomal dominant polycystic kidney disease (1); benign ovarian tumor (1); bipolar disorder (1); brain cancer (1); brain hemorrhage (1); bronchopulmonary dysplasia (1); Calcium nephrolithiasis (1); Cerebral ischemia (1); chronic kidney disease (1); Crohn disease (1); dementia (1); diabetic cardiomyopathy (1); endometriosis (1).
A further 28 diseases each share a sentence with TRPC3 in 1 paper.